RN7SL861P (RNA, 7SL, cytoplasmic 861, pseudogene)
Gene: Miscellaneous RNA gene on chromosome 1 (162,777,730 to 162,778,014, forward strand). Ensembl gene ENSG00000243173.
Homologues: Orthologues: chimpanzee Metazoa_SRP (99% identical), macaque Metazoa_SRP (93% identical). Paralogues in human: RN7SL1 (81% identical), RN7SL2 (81% identical), RN7SL3 (80% identical), RN7SL326P (80% identical), RN7SL147P (79% identical), RN7SL45P (79% identical), RN7SL709P (79% identical), RN7SL717P (79% identical), RN7SL126P (79% identical), RN7SL218P (79% identical), RN7SL575P (79% identical), RN7SL478P (79% identical), and 705 more.